CD69 (CD69 molecule)
Diseases named in the same sentence as CD69 in open-access papers (continued):
Sharing a sentence is not in itself a finding about the gene and the disease.
inflammatory bowel disease (11 papers, 2013 to 2023). A spectrum of small and large bowel inflammatory diseases of unknown etiology. "Compared to CD69- cells, CD69+ Tregs were found to be more effective in maintenance of immune tolerance and only CD69+ Tregs were able to prevent the onset of inflammatory bowel disease (IBD) in mice." (PMID 35165293, 2022). "The involvement of the CD69-Myl9 system in airway inflammation and inflammatory bowel diseases has been demonstrated, however, its contribution to KD vasculitis has not been investigated." (PMID 36685558, 2022). "More recently, Zundler and colleagues reported that CD103+ tissue-resident memory Th cells accumulated in the mucosa of patients with inflammatory bowel disease, and that the presence of CD69+ ThCD103 cells was predictive of flares." (PMID 33774709, 2021). "This is in line with earlier literature highlighting the importance of CD69 in inflammatory bowel disease." (PMID 32248339, 2020). "Here, we aimed to investigate the role of CD69 in accumulation of CD4 T cells in intestine using murine models of inflammatory bowel disease." (PMID 23776480, 2013). "Moreover, adoptive transfer of CD69+ Tregs but not CD69−Tregs or CD69+ Tregs deficient in IL-10 dramatically prevented the development of inflammatory bowel disease (IBD) in mice." (PMID 30185773, 2018). "Moreover, our mAb administration experiments revealed that CD69 could be a potential therapeutic target for inflammatory bowel disease." (PMID 23785429, 2013). "The CD69-Myl9 system is reported to be involved in the pathogenesis of airway inflammation, polyp formation of eosinophilic rhinosinusitis (ECRS) patients, and inflammatory bowel diseases, such as ulcerative colitis and Crohn’s disease." (PMID 36685558, 2022).
colorectal cancer (10 papers, 2019 to 2025). A primary or metastatic malignant neoplasm that affects the colon or rectum. "Higher CD69 expression on CD19+ B-cells was reported with longer survival in colorectal cancer.Understanding the complexity of the polarization of T- or B-cell subsets, myeloid cell types in response to ICI therapy is the focus of the current research." (PMID 37901220, 2023). "CD4+ TAI subsets co-expressing inhibitory PD-1 and activating ICOS as well as CD39 and CD69 were detectable in freshly resected colon tumor from MMRd colorectal cancer patients known to express neo-epitopes due to accumulated point-mutations." (PMID 31412943, 2019). "Taking into account phase I and phase II clinical trials of patients with colorectal and ovarian cancer treated with GM102, it was shown that in the case of colorectal cancer the number of blood monocytes CD69+ increases, while the number of CD69+ activated-regulatory T cells decreases." (PMID 39351532, 2024). "In colorectal cancer liver metastases isolated from human samples, two main subsets of TRM cells were identified as CD103+CD69+ or CD103-CD69+ TRM." (PMID 40862776, 2025). "We also measured T cell activation against a collection of CEA-positive or CEA-negative cell lines, including three patient-derived CEA-positive colorectal cancer cell lines, using a Jurkat reporter cell line (J69), modified by CRISPR to express tdTomato under the control of the CD69 promoter." (PMID 36405739, 2022). "Additionally, utilizing a syngeneic colorectal cancer model in which VDR/PD-L1 co-upregulation occurs in vivo under radiation therapy (RT), MeTC7 inhibits PD-L1 and enhances intra-tumoral CD8+T cells expressing lymphoid activation antigen-CD69." (PMID 37444542, 2023). "Anti-DKK2 treatment induced significant increases in GZMB and CD69 over control IgG treatment in the DKK2high, but not DKK2low sample group, suggesting that DKK2 blockade activates infiltrating CD8+ T cells in human colorectal cancers that express high levels of DKK2." (PMID 32559853, 2020).
pancreatic cancer (10 papers, 2018 to 2025). "We report stimulation of human healthy donor NK cells exposed to MV-infected colorectal or pancreatic cancer cells, as indicated by increased CD69 expression compared to mock-infected controls." (PMID 36765035, 2023). "Gemcitabine increases the IFN-gamma production by activated T-cells and CD69+ cells in pancreatic cancer patients, and augments the cell-mediated immune response in small-cell lung cancer patients (phase I clinical trial)." (PMID 29849947, 2018). "NK cells readily exerted cytotoxicity against PANC-1 cells as reflected by acquisition of the activation marker CD69 and the degranulation marker CD107a by the NK cells and by the expression of apoptosis markers by the pancreatic cancer cells at 4 hours of coculture." (PMID 38598844, 2024). "Besides, our study also revealed that co-culturing with DKK3-overexpressing pancreatic cancer cells promotes the expression of CD69, CD3, CD25, CD71, and HLA-DR mRNA in CD4+ T cells." (PMID 34391478, 2021). "To confirm whether degranulation of perforin and granzyme-B changes when NK cells attack HER2-high-expressing human pancreatic cancer cell line in the presence of Tmab and/or αCD137, we stained intracellular perforin, granzyme-B and cell surface CD69 of NK cells." (PMID 30596643, 2018). "(F) Comparative surface expression of activation marker (CD69), activating receptors (NKp46, NKG2D), and exhaustion marker (TIM-3) on conventional NK (cNK) cells and trNK cells isolated from orthotopic pancreatic tumors." (PMID 39656086, 2024).
co-infection (9 papers, 2016 to 2026). "The finding of a more ‘HCV-like’ phenotype in HIV-HCV co-infection suggests that reduced CD69 expression might also be caused by an increase of CD56bright NK cells that lack CD69 in the HIV-HCV co-infected cohort." (PMID 27091211, 2016). "The reduced expression of CD69 in HIV-HCV co-infected cohort suggests a decreased activation status of CD56bright NK cells in HIV-HCV co-infection than HIV mono-infection." (PMID 27091211, 2016). "The CD56bright NK cell subset was activated in HIV-HCV co-infection as assessed by the expression of CD69 as compared to healthy controls but was significantly downregulated in comparison to HIV mono-infection." (PMID 27091211, 2016). "Moreover, Ad5/3-DMFE was significantly superior to all other viruses regarding IFNγ secretion and to the co-infection strategy regarding CD69 expression on CD8+ T cells." (PMID 41552759, 2026). "To assess the impact of cART + 3HP on T cellactivation, we studied expression of HLA-DR and CD69 on CD4+ T cells in BAL atweek 11 post Mtb infection (or 2 weeks post SIV co-infection, prior toinitiation of cART + 3HP) and at necropsy (end of 12 weeks of cART + 3HP treatment) in all4 study groups." (PMID 39257997, 2024). "Thus, HIV-HCV co-infection is able to modulate the phenotype of CD56bright NK cell subset in a unique way such that NKp46 and CXCR3 expressions are distinct for co-infection while both mono-infections have an additive effect on CD56bright, CD69 with CD95 expressions." (PMID 27091211, 2016). "In contrast to CD69 expression, CD95 expression in HCV mono-infection was decreased when compared to HIV mono-infection and HIV-HCV co-infection." (PMID 27091211, 2016). "Interestingly, the frequency of circulating MAIT cells expressing the early activation marker CD69 trended significantly higher following Mtb co-infection in SIV+ animals, but not in the SIV-naïve cohort." (PMID 32433713, 2020).
myeloma (9 papers, 2017 to 2025). "Cytotoxic activity against myeloma cells is limited to CD69- TTE encompassing oligoclonal expanded TTE which circulate between BM and PB in NDMM patients." (PMID 33708212, 2021). "When expressed on Jurkat T cells, FcεRIα-based CARs mediated robust responses in terms of CD69 upregulation to U266 myeloma cells expressing low levels of mIgE." (PMID 30364107, 2018). "In summary, prior to advanced 5T33 myeloma burden, there are splenic PD-1+ T cells that appeared to be chronically activated, as demonstrated by expression of activation markers CD69, OX-40 and CD103, and inhibitory receptors LAG-3 and TIM-3." (PMID 28642819, 2017). "The balance between CD69- and CD69+ cells within the bone marrow-TTE compartment may regulate immune responses in new diagnosed multiple myeloma and contribute to the clinical disease heterogeneity." (PMID 34603332, 2021). "BM-resident CD69+ TTE may potentially have a beneficial effect against myeloma by recruiting oligoclonal expanded cytotoxic CD69- TTE and maintaining dormancy of the malignant clone." (PMID 33708212, 2021). "Tracing BM-resident CD69+ TTE within MILs and correlating their numbers with clinical outcome in MM patients receiving MILs as adoptive T-cell therapy could provide essential insights into the role of BM-resident CD69+ TTE in myeloma immunity." (PMID 33708212, 2021). "Also, the frequency of IFN-producing or CD69-expressing γδT cells was higher in myeloma patients." (PMID 37187728, 2023). "In eight of these, we examined 12 surface markers commonly used in myeloma research, while in four cases we studied only a subset of them (CD38, CD44, CD45, CD49d, CD69, CD86, CD138, and CD184)." (PMID 39493694, 2024). "The documentation of a unique relationship between BM-resident CD69+ TTE and circulating cytotoxic CD8+ TTE in myeloma is of great interest, as the cardinal feature of TRM cells is a lack of equilibration with the circulating memory T-cell pool." (PMID 33708212, 2021). "BM-resident CD69+ TTE are not restricted to myeloma, comprise approximately half of CD8+ TTE in the BM of healthy controls, and a small proportion of CD8+ TTE in the BM of MGUS patients." (PMID 33708212, 2021). "Alternatively, the accumulation of CD69+ TTE within MILs may contribute to local inflammation through the production of the pro-inflammatory cytokines IFN-γ and TNF-α and promote myeloma growth." (PMID 33708212, 2021). "We furthermore suggest that a competitive flux, or equilibrium, between BM-resident CD69+ TTE and circulating CD69- TTE regulates the egress of myeloma-reactive CD69- TTE from the BM to PB and contributes to senescence (CD69-PD-1lo TTE) or exhaustion (CD69+PD-1hi TTE) of CD8+ TTE." (PMID 33708212, 2021). "Low perforin and granzyme expression by BM-resident CD69+ TTE rule out their contribution to cytotoxic activity against myeloma cells." (PMID 33708212, 2021). "Thus, the balance between CD69− TTE and CD69+ TTE cells may likely regulate anti-myeloma responses and contribute to clinical heterogeneity in MM patients." (PMID 35563634, 2022). "Furthermore, myeloma and leukemic cell lines H929, THP1 and K562 did not induce CD69 expression in the γδTCR3-4 Jurkat76 cells." (PMID 38321065, 2024).
ovarian carcinoma (9 papers, 2012 to 2025). A malignant neoplasm originating from the surface ovarian epithelium. "The CD16-positive NK-subset was significantly activated by monocytes (upregulation of CD69) which is likely to explain the enhanced natural cytotoxicity against various ovarian cancer cells." (PMID 23036052, 2012). "Linear regression analysis of our Proseek® data had found six of these proteins to have a statistically significantly trend (p < 0.001); CA125, CXCL13, CD40L, CD69, and LAP.TGF-β1 levels were higher in ovarian cancer serum samples, while EGFR levels were lower." (PMID 29051715, 2017). "Importantly, the effector and co-stimulatory molecules CD69, CD25, OX40, and 4-1BB that were identified in the scRNAseq analysis also proved to be upregulated at the protein level on GPR56-positive TILs from three different ovarian cancer donors." (PMID 35804934, 2022). "Thus, we determined the expression of CD69 on NK cells and release of IFN-γ in the presence of monocytes and evaluated the cytolytic NK cell activity by the expression of CD107a after additional co-culture with different human ovarian cancer cell lines." (PMID 23036052, 2012). "No expression of CD69 was observed following coculture with an irrelevant target, CD22− SKOV3 human ovarian cancer cells." (PMID 38596311, 2024). "Robust upregulation of early T-cell activation marker CD69 was detected by flow cytometry for all three FOLR1-targeting biAbs and both ovarian cancer cell lines when compared to the negative control." (PMID 31497024, 2019).
glioblastoma (8 papers, 2021 to 2025). The most malignant astrocytic tumor (WHO grade IV). "Flow‐cytometric analysis of glioblastoma immune infiltrates showed a significantly higher frequency of T lymphocytes expressing PD‐1, CD69, and CD103." (PMID 40498413, 2025). "Compared to healthy individuals (n = 15) the proportion of activated NK cells (CD3+/CD69+) in glioblastoma patients who remained progression-free for 6 months (**p < 0.01) was significantly higher." (PMID 34079819, 2021). "This in vitro stimulation resulted in a similar upregulation of the frequency and density of activatory NK cell receptors such as CD94+ and CD69+ on NK cells to that observed in glioblastoma patients." (PMID 34079819, 2021). "In addition, the potential of CD69 as a biomarker of ICI response in patients with glioblastoma was assessed." (PMID 41019666, 2025). "This suggests that in glioblastoma patients, these cells lack the ability to be fully activated when primed, as evidenced by the reduced levels of IFNγ and CD69, which allows speculation that these cells may be terminally exhausted." (PMID 39513882, 2024). "The present study provides first evidence that low Hsp70 levels and elevated proportions of activated CD94+/CD69+ NK cells able to recognize mHsp70+ tumor cells in glioblastoma patients might favor a beneficial clinical outcome." (PMID 34079819, 2021). "Importantly, the proportion of activated NK cell subsets (CD56+/CD94+, CD3-/CD69+) was significantly greater in glioblastoma patients at diagnosis, as compared to healthy controls (Kruskal Wallis test, *p < 0.05)." (PMID 34079819, 2021). "Subsequent reductions in the positivity of the cell activation marker CD69 and the key pro-inflammatory cytokine IFNγ were also observed in CD4+ and CD8+ T cells and NK cells from glioblastoma patients." (PMID 39513882, 2024). "We examined the percentage of TIM-3 positivity and the activation status (via CD69 and IFNγ) following the PMA and ionomycin stimulation of glioblastoma patients’ T and NK cells compared to those of healthy individuals." (PMID 39513882, 2024). "These pro-inhibitory changes are also correlated with reduced levels of the activation marker CD69 and the pro-inflammatory cytokine IFNγ in CD4+ and CD8+ T cells, as well as NK cells from glioblastoma patients." (PMID 39513882, 2024). "CXCR6, an established marker of CD69+CD103+ Trm cells, was expressed on CD4+ Trm cells as anticipated, but also enriched in all other CD4+ T-cell subsets in glioblastoma compared to blood." (PMID 35464424, 2022). "Interestingly, we have recently shown that peripheral T and NK cells from glioblastoma patients display greater levels of TIM-3 and lower activity markers CD69 and IFNγ compared to T and NK cells from healthy individuals." (PMID 41516291, 2025). "In murine glioblastoma models undergoing immune checkpoint inhibitor therapy, [18F]AlF-NOTA-CD69 antibody selectively accumulated in tumors treated with immune checkpoint inhibitors, correlating strongly with increased CD69 expression on tumor-infiltrating lymphocytes." (PMID 41019666, 2025). "However, we saw a significant reduction in the percentage of CD69 and IFNγ positivity in PMA and ionomycin-stimulated CD4+ and CD8+ T cells and NK cells from glioblastoma patients compared to their counterparts in healthy donors." (PMID 40072074, 2025). "However, a significantly reduced level of induction of CD69 percentage positivity was seen on stimulated CD4+ and CD8+ T cells and NK cells from glioblastoma patients compared to healthy donors." (PMID 39513882, 2024).
liver fibrosis (8 papers, 2019 to 2023). "Evaluation of the activation markers CD25 and CD69 showed that PD-1 expression was significantly associated with an activated NK cell phenotype in persons with mild and advanced hepatic fibrosis." (PMID 38107019, 2023). "Liver fibrosis caused significant elevation on the percentage of CD4+CD69+ and CD8+CD69+cells in comparison to naïve group in the spleen." (PMID 35307625, 2022). "Our results also found a higher expression of CD69 in peripheral iNKT cells from NAFLD patients with significant liver fibrosis." (PMID 35052736, 2021). "Here, we evaluated CD69, CD25, NKp46 and NKp30 cell markers but only PD‐1 expression was associated to liver fibrosis progression." (PMID 31536177, 2019). "We found an increase in iNKT and CD69+iNKT cells in NAFLD patients with significant liver fibrosis, suggesting that CD69+iNKT cells could be a biomarker of liver fibrosis progression in NAFLD." (PMID 35052736, 2021). "These correlations reinforce our hypothesis of the possible role of CD69+iNKT as a biomarker of liver fibrosis progression." (PMID 35052736, 2021). "Moreover, the percentages of CD69+ ILC2s were positively correlated with aggravation of liver fibrosis in patients with liver diseases, suggesting that ILC2s may contribute to the immunopathology of liver fibrosis." (PMID 32708044, 2020). "Furthermore, we found a positive correlation between CD69 expression in iNKT cells and FIB4, a liver fibrosis index, and AST, a strong predictor of hepatocellular injury and acute liver failure." (PMID 35052736, 2021). "Regarding the cellular activation profile, NAFLD with significant liver fibrosis (F ≥ 2) displayed higher levels of CD69+iNKT cells compared to NAFLD with none or mild liver fibrosis (F ≤ 1) and control patients." (PMID 35052736, 2021). "There was also an increase in the percentage of CD69+iNKT cells in DILI patients (25.3 ± 9.4) with respect to NAFLD patients without significant liver fibrosis (F ≤ 1) (6.1 ± 2.5, p = 0.045) and healthy controls (10.1 ± 1.9, p = 0.042)." (PMID 35052736, 2021). "A team found that CD69+CD103-CD8+ Trm was enriched when hepatic fibrosis subsides in NASH mouse, and confirmed that CD8+ Trm could attract HSCs and mediate apoptosis through Fas/FasL pathway, leading to the resolution of hepatic fibrosis." (PMID 38086792, 2023). "Interestingly, NAFLD patients with significant liver fibrosis (F ≥ 2) had increased the percentage of CD69+iNKT cells (26.9 ± 6.6) with respect to those without significant liver fibrosis (F ≤ 1) (6.1 ± 2.5, p = 0.040) and healthy control (10.1 ± 1.9, p = 0.031)." (PMID 35052736, 2021).
lymphopenia (8 papers, 2016 to 2025). Reduction in the number of lymphocytes. "Our findings support the suggestion that cytokines, particularly in CM, may promote the transient sequestration of lymphocytes in secondary lymphoid tissue, potentially causing the observed paradoxical lymphopenia by contributing to the upregulation of CD69 that is recognized in CM." (PMID 28122790, 2017). "Manual gating confirmed that high CD69 expression on MAIT cells is associated with a fatal outcome, organ dysfunction (assessed by the Δ‐SOFA score) and lymphopenia." (PMID 40041474, 2025). "Less pronounced lymphopenia (p = 0.02), a trend towards a lower expression of CD69 count (p = 0.07), and antigen-stimulated ICAM-1 (p = 0.01) were found in the verum group." (PMID 27478305, 2016). "Acute infection often involves lymphopenia and a predominance of CD8+ T cells expressing CD69, CD107a, granzyme B, and perforin, targeting virus-infected cells." (PMID 39596565, 2024). "At the same time that this lymphopenia occurred, we observed extensive activation of circulating cytotoxic T cells and helper T cells in young and aged mice 3 days after MCAO as indicated by CD69 expression." (PMID 27115295, 2016).